EPHA2 (EPH receptor A2)
Diseases named in the same sentence as EPHA2 in open-access papers (continued):
Sharing a sentence is not in itself a finding about the gene and the disease.
tumor (continued). "Mice that received EphA2 photoimmunotherapy treatment exhibited notable tumor growth inhibition in comparison with the control animals." (PMID 35776159, 2023). "Stimulation of EphA2 by its ligands induces phosphorylation of tyrosine-588 residues (pY588-EphA2), which function as tumor suppressors." (PMID 37712876, 2023). "Disparities between tumour-suppressor and tumour-promoter actions are at least partly attributable to differences in ligand-dependent and ligand-independent signalling, as shown for EphA2 and EphB4." (PMID 36830852, 2023). "The ligand-induced dimerization and oligomerization of EphA2 trigger tumor-suppressive signaling, while the EphA2 monomer exhibits pro-tumorigenic activity." (PMID 37816703, 2023). "HIFU ablation induced residual tumor angiogenesis by up-regulating HIF-2α/VEGFA/EphA2 pathway in HCC." (PMID 36814489, 2023). "In HCC cells, EPHA2 was identified as the receptor responsible for inducing self-renewal and tumor-initiating ability in response to ephrinA3 or hypoxia stimulation." (PMID 37444544, 2023). "EPHA2 has attracted the attention of the research community due to its involvement in tumor capillary formation." (PMID 36769332, 2023). "The results showed that higher levels of AC005392.2, GLUT1, and EPHA2 were found in tumor tissues than in surrounding normal tissues." (PMID 38044399, 2023). "The major function of these linkers is to hold the segment of the drug and EphA2 peptide together sufficiently enough for the ligands to be attached specifically to the target receptors on the cancer cells/tumor." (PMID 37530973, 2023). "In a mouse model of pancreatic adenocarcinoma, decreased EphA2 expression using siRNA suppressed tumour development and progression, including invasion and metastasis." (PMID 36830852, 2023). "EphA2-CAR.C7R T-cells induced complete regression of GBM U373 tumor xenografts at a cell dosage where unmodified EphA2-CAR T-cells were ineffective." (PMID 38136398, 2023). "Clinically, tumor samples from breast patients with less response to neoadjuvant chemotherapy showed a high level of EphA2 pS897 expression." (PMID 37063424, 2023). "In the patients cohort, EPHA2 mRNA level was significantly elevated in tumor tissue specimens compared to normal specimens (p-value < 0.001)." (PMID 38008720, 2023). "The ATP-competitive tyrosine kinase inhibitor ALW-II-41-27 (ALW) of EphA2 has been shown to inhibit the growth of a variety of tumour cells in vitro and in vivo." (PMID 37980165, 2023). "They observed that EPHA2 overexpression promotes colony formation and facilitates tumor growth, primarily through Akt (T308)/mTORC1 activation." (PMID 37444544, 2023). "Several studies using cultured cells have demonstrated that EphA2 overexpression increases tumor cell growth, motility, and metastasis and expression of EphA2 alone in human mammary epithelial MCF10A cells is sufficient to confer tumorigenicity in mice." (PMID 37712876, 2023). "As the non-canonical pathway is considered oncogenic, ADAM17 mediates EphA2 pS897-dependent tumor growth and (IR-induced) cell migration." (PMID 36998455, 2023). "EphA2 inhibition reduced phosphorylation of apoptotic agonist BAD and caused apoptosis in NSCLC tumours in mice, blocking tumour growth." (PMID 36830852, 2023). "Subsequently, a range of Eph receptors have been identified as preferentially expressed on tumours, of which EphA2, EphA3, and EphB4 have been a particular focus for therapeutic targeting." (PMID 36830852, 2023). "The combination treatment (EphA2 photoimmunotherapy plus anti-PD-1) elicited a notable reduction of tumor growth in comparison to each monotherapy treatment." (PMID 35776159, 2023).
tumor (continued). "EphA2-SE exerts an oncogenic role by recruiting different transcription factors to drive the expression of the oncogene EphA2, thereby promoting tumor progression." (PMID 37446021, 2023). "In contrast, the expression of its ligands in tumor tissues is suppressed, which prompted us to characterize the tyrosine kinase-independent function of EphA2 in the tumor microenvironment." (PMID 37059179, 2023). "EPHA2, an Eph receptor known to interact with ephrinA5, has been reported to have not only tumor suppressive but also pro-oncogenic functions." (PMID 37880732, 2023). "In this tumor model, the progranulin/EphA2 axis drives tumor cell migration, invasion, anchorage-independent growth, in vivo tumor formation and cisplatin-resistance." (PMID 36980592, 2023). "In brain slices from a GBM6 tumor-bearing mice model six days after the injection of α-EGFRvIII synNotch–α-EphA2/IL13Rα2 CAR-T cells, primed T cells and apoptosis cells can be detected only in tumor sites." (PMID 36983174, 2023). "We found that 25.0% intestine- and 37.8% esophagus-specific proteins, such as ELF3 and EPHA2, respectively, were upregulated in the tumor tissues, whereas 77.1% stomach-specific proteins, such as MUC5AC, were downregulated." (PMID 36788224, 2023). "Previous studies have shown that EphA2 silencing was effective in reducing tumor burden in combination with chemotherapeutic agents such as paclitaxel and docetaxel." (PMID 36835335, 2023). "Further in vivo experiments on the xenograft transplantation mouse model with limiting dilution HCC1806 cells revealed remarkably lower frequencies of tumor formation upon EphA2 knockdown." (PMID 37063424, 2023). "It is established that the IgLON family member OPCML acts as a tumor suppressor by eliciting the downregulation or the inhibition of RTKs, such as EphA2, FGFR1, FGFR3, HER2, HER4, and AXL." (PMID 37765276, 2023). "The tyrosine kinase EphA2, belongs to the family of Eph receptors and is highly expressed in tumor cells." (PMID 37612696, 2023). "Tumours derived from EphA2 null mice showed a substantial reduction in tumour volume compared to wild-type mice and an increase in tumour cell death." (PMID 36830852, 2023). "EphA2 is thus, by its transactivation, involved in many oncogenic processes, such as tumor cell proliferation, survival and metastasis, and is associated with a poor prognosis in TNBC patients." (PMID 38072918, 2023). "Suppression of EphA2 expression in cells derived from pancreatic adenocarcinoma, through sequence-specific siRNA, leads to delayed tumor growth in a mouse xenograft model." (PMID 36142306, 2022). "For mice exposed to irradiation, it was recognized that tumor volume, weight, and EphA2 expression were all suppressed." (PMID 36090890, 2022). "Herein, EphA2-siRNA was encapsulated in liposomal nanoparticles 1,2-dioleoyl-sn-glycero-3-phospahtidylcholine (DOPC) and combinedly termed as EPHARNA (EphA2-siRNA-DOPC) for their specifically target of EphA2 expression in the tumor." (PMID 35456698, 2022). "Studies have, for example, demonstrated that EPHA2 can act both as a tumour promoter and a tumour suppressor, depending on its phosphorylation status." (PMID 35008410, 2022). "Angiogenesis of tumor cells was promoted by the migration and sprouting of EphA2‐specific endothelial cells and the increased expression of vascular endothelial growth factor." (PMID 35587712, 2022). "By inducing receptor endocytosis, 1C1 can be employed to deliver cytotoxic agents to tumor cells overexpressing EphA2." (PMID 36142306, 2022). "Regions of the tumour within 500 μm of the prostate margin have increased expression of EphA2, pEphA2S897 and pMLC2, indicative of aggressive invasive MAT as compared with regions of adjacent normal glandular architecture." (PMID 35869144, 2022). "Based on its high expression in human CRPC, we herein intend using CRISPR platform to achieve knockout of EphA2 to slow tumor progression." (PMID 36588949, 2022).
tumor (continued). "EGFR and EphA2 were expressed at significantly higher levels in cancer tissues than in normal tissues, and levels increased to significant degrees with advancing tumor cell grade." (PMID 35668076, 2022). "More specifically, it was demonstrated that the direct communication among membrane protein (EPHA2) on exosomes and recipient cells resulted in stimulation of tumor endothelial cells." (PMID 35408909, 2022). "Ephrin type‐A receptor 2(EphA2) is expressed more abundantly in tumor tissues compared to most normal tissue." (PMID 35587712, 2022). "More importantly, the phenotypes of GRN- and EphA2-deleted cells were very different in terms of cell migration, invasion, adhesion and in vivo tumor formation." (PMID 36471440, 2022). "Collectively, anlotinib inhibited tumor angiogenesis of radioresistant EC cells by inhibiting EphA2." (PMID 36090890, 2022). "Given the pivotal roleof EphA2 in tumor progression, we are confident that the agents reportedcould be further developed into innovative EphA2-targeting therapeutics." (PMID 36331527, 2022). "UniPR126 has been recently employed as a cargo to generate a mixed nanomicellar delivery tool specific for EphA2 overexpressing tumor cells." (PMID 36142306, 2022). "Following the infection, increased EPHA2 activation was observed, resulting in decreased BC cell viability in soft agar assays, as well as in vivo inhibition of tumor formation." (PMID 36499598, 2022). "In the cross-tables, high EPHA2 expression was positively correlated with tumor proliferative capacity (Ki-67 LI) (p = 0.0115), whereas no other significant associations were noted." (PMID 35204461, 2022). "By studying the migration, invasion and matrix remodeling of tumor cells to investigate the formation mechanism of VM, such as VE-cadherin, ephrin type-A receptor 2 (EphA2) and phosphoinositide 3-kinases (PI3K) are involve in VM formation." (PMID 35595748, 2022). "The targeting of EPHA2, EPHA10, EPHB4, ephrin-A2, ephrin-A4, as well as ephrin-B2 in BC cells or xenograft models is associated with apoptosis induction, tumor regression, anticancer immune response activation, and impaired cell motility." (PMID 36499598, 2022). "EA5 induces reduction of EphA2 expression in vitro, and treatment with this mAb also blocks the growth of several tumor cell lines." (PMID 36142306, 2022). "EphA2 signalling has also been shown to induce migratory behaviour in epithelial cells, thereby promoting tumour progression by driving invasion and metastasis." (PMID 35869144, 2022). "Within this study, we found that expression of EphA2 and pEphA2S897 was spatially regulated within tumour lesions." (PMID 35869144, 2022). "Consistently, ANXA1 binding to EphA2 increased EphA2 levels and its oncogenic activity, enhancing tumor growth and metastatic dissemination in vitro and in vivo." (PMID 36247003, 2022). "All cells generated tumor xenografts, with parental and EphA2 KO MSTO-211H cells showing similar in vivo tumor formation." (PMID 36471440, 2022). "The use of ScFv immune phage-display libraries has already shown good results in the development of human therapeutic recombinant antibodies for tumor-targeted therapy EphA2, and in the discovery of ScFv against IL1RAP from a human library." (PMID 36293532, 2022). "VM is necessary for rapid tumor proliferation, and EphA2 and VEGFA are important molecules in this process." (PMID 35595748, 2022). "This proteolytic event abrogates tumor-suppressive forward signaling and promotes oncogenic ligand-independent signaling, thereby converting EphA2 from a tumor suppressor to an oncoprotein." (PMID 35780836, 2022). "We performed whole-genome bisulfite sequencing and confirmed that the methylation level in promoter region corresponding to the two critical probes at EPHA2 promoter from TCGA_GBM was negatively related with EPHA2 mRNA level in the four tumor samples." (PMID 35105853, 2022).
tumor (continued). "The receptor tyrosine kinase EphA2 inits ephrin-bound form functionsas a tumor suppressor, preventing cancer cell migration, tumor growth,and angiogenesis." (PMID 36331527, 2022). "Upon EphA2 cleavage by MT1-MMP, this effect was significantly hampered; thus, EphA2 shedding by MT1-MMP converts a tumor-suppressive RTK to an oncoprotein." (PMID 36132127, 2022). "Further research has revealed that EphA2 and ephrin-A1 are also expressed in other solid tumors and contribute to tumorigenesis, angiogenesis, and tumor invasion." (PMID 35448036, 2022). "Rao and colleagues reported that inhibition of HSP90 resulted in proteasome-dependent degradation of its client oncoprotein EphA2 and, hence, increased tumor recognition by EphA2-specific CD8+T lymphocytes." (PMID 33815422, 2021). "The crosstalk between EphA2 and BrCa oncogenic pathways promotes tumor cell malignancy in ligand-independent signaling." (PMID 33977106, 2021). "We found that the knock‐down of EphA2 significantly reduced cell proliferation, transwell migration, cell migration and tumour sphere formation." (PMID 33586348, 2021). "Because ligand-bound EphA2 turns the oncogenic receptor into a tumor suppressor, the design of ephrin mimetics, hence synthetic agonistic EphA2-targeting agents, represents a potentially therapeutically-viable strategy." (PMID 34204178, 2021). "It is believed that this imbalance of EphA2 and ephrinA1 results in both increased ligand-independent signaling and a decreased ligand-dependent signaling, promoting tumor growth and malignancy." (PMID 33277361, 2021). "BiTE-secreting cells were cytotoxic against EphA2-positive tumour cell lines in vitro and capable of recruiting cytotoxic bystander T cells." (PMID 34885108, 2021). "Its tumour-promoting activities were found to be exerted via a ligand-independent mechanism involving the phosphorylation of EphA2’s serine 897 residue." (PMID 33430066, 2021). "As highlighted above, EphA2 plays an important role in a number of cancers; however, its role is context-dependent, and it can act as either a tumour promoter or tumour suppressor." (PMID 33430066, 2021). "EPHA2 and ephrin-A1 overexpression, along with elevated MVD, was associated with the tumor TNM stage and the presence of perineural and perivascular invasion." (PMID 34445116, 2021). "Depletion of EphA2 in purified ALDHpositive cells markedly inhibited their tumor-forming ability in vivo." (PMID 33572284, 2021). "It will be interesting to explore how the signalling downstream of EphA2 differs between this tumour-suppressive process and the pro-invasive nuclear-capture-dependent pathway that we describe in this this study." (PMID 34819513, 2021). "Phosphorylation of EphA2 at S897 is important for signaling status in different tumor cells including NSCLC." (PMID 33671073, 2021). "EPHA2 modulates tumor invasion and metastasis by negatively regulating CDH1 (E-cadherin), while also having a positive correlation with vimentin and β-catenin expression." (PMID 34455105, 2021). "Hsu and colleagues reported an increase in EphA2-negative tumor cells following experimental EphA2 CAR treatment of OS." (PMID 34503279, 2021). "It has been reported that EPHA2 promotes malignant tumor progression by enhancing the AKT/mTOR signaling pathway." (PMID 33834064, 2021). "Associated studies have shown that EphA2 is upregulated in EWS cells, and participates in endothelial cell migration toward tumors to assist with tumor angiogenesis." (PMID 34566963, 2021). "Similar to the earlier CT2A studies, infected and uninfected 67 C-4 tumor cells express abundant EphA2 on their surface." (PMID 34599026, 2021). "EPHA2 expression was then correlated with tumor histological features, various clinicopathological parameters, and patients’ outcomes." (PMID 34445116, 2021). "A conspicuous amount of evidence suggests that ligand-mediated activation of EphA2 has tumor-suppressive functions." (PMID 33572284, 2021).
tumor (continued). "Our functional data of blocking EphA2 on three different solid tumor cell lines by CRISPR/Cas9 had significantly modified Vδ1 γδ T-cell-mediated tumor lysis." (PMID 34691070, 2021). "RNA-seq data analysis showed that EphA2-SE participates in the growth and metastasis of three tumor cell types." (PMID 33712565, 2021). "We propose that tissue context is pivotal to understanding the different roles of EphA2 in tumor biology." (PMID 33891893, 2021). "Immunohistochemical staining for EphA2 revealed that EphA2 was predominantly expressed in tumor cells within bone and associated blood vessels, consistent with what we observed in human disease." (PMID 33869989, 2021). "Nonetheless, our current results provide evidence indicating that ephrinA5 can hinder the tumor suppressive signaling normally coupled with degradation of EphA2, thus allowing the oncogenic receptor to function at the HGSC cell membranes." (PMID 33893375, 2021). "The quantitative real–time PCR analysis showed once again that EPHA2 mRNA levels were higher in primary tumor tissues than in surrounding normal tissues." (PMID 34831119, 2021). "Specifically, EphA2 overexpression is found in breast, ovarian, prostate, and pancreatic cancers and is correlated with aggressive tumors, high rates of tumor recurrence, and poor patient prognosis." (PMID 33277361, 2021). "ALW-II-41-27 is a potent EphA2 inhibitor, which has displayed antitumoral activity in different tumor types and preclinical models." (PMID 34831119, 2021). "Our models support an indirect role for tumor‐expressed EphA2 in modulating osteoclast differentiation through regulation of IL‐6." (PMID 33869989, 2021). "It will be of great interest to determine the role other cytokines differentially regulated by EphA2 in tumor cells play in modulating osteoclast differentiation and function." (PMID 33869989, 2021). "In summary, we reported that the level of EphA2 expression is positively correlated with CC tumour proliferation, invasion, patient overall survival and therapeutic resistance of CC to EPI." (PMID 33586348, 2021). "The tumor-suppressive signaling elicited by EphA2-ephrinA complexes is often halted in aggressive cancers via EphA2 receptor overexpression coupled with ephrinA ligand downregulation." (PMID 33893375, 2021). "In our study, we discovered a super-enhancer at about 15 kb upstream of EphA2 that is present in various tumor cells, including A549, HeLa, MCF-7, HCT-116, Panc-1, T24, MKN45, BT16, A498 and K562 cells from super-enhancer databases." (PMID 33712565, 2021). "Virus-based EphA2 expression induces a robust acquired antitumor immune responses in both an oHSV-resistant murine brain and peripheral tumor model." (PMID 34599026, 2021). "The elevated expression of EphA2 is correlated with tumor deterioration and poor prognosis of cancer patients." (PMID 33879771, 2021). "Conversely, an increase in tumor cell motility and invasion was observed upon S897 phosphorylation of EphA2 in combination with anti-VEGFR2 treatment." (PMID 35096972, 2021). "Another attractive feature of EphA2 is its rather low physiological expression in healthy adult tissues, making EphA2 an interesting target with predictably few on-target, off-tumor side effects." (PMID 34831119, 2021). "Due to its role in tumor progression and invasiveness and its potentially safe profile with limited expression on normal tissue, EphA2 is a promising target for CAR T–cell immunotherapy of PBTs that demands further clinical and preclinical investigation." (PMID 34760690, 2021). "Our results reveal that EphA2-SE deletion can inhibit tumor cell growth and tumor progression by directly modifying the expression of the adjacent EphA2 gene." (PMID 33712565, 2021). "To determine if this was unique to this one tumor model, we next examined C170 activity in an EphA2 (+) syngeneic MPNST model." (PMID 34599026, 2021).